EGFR (epidermal growth factor receptor)
Diseases named in the same sentence as EGFR in open-access papers (continued):
Sharing a sentence is not in itself a finding about the gene and the disease.
tumor (continued). "An important distinction between previous studies and our own is that previous studies manually assessed IHC-based EGFR and CK5/6 expression and therefore counted only EGFR-positive and CK5/6-positive tumor cells." (PMID 29409530, 2018). "Other examples of tumor cell survival kinases include MEK1, MEK2, mTOR, and S6 kinase which are all downstream members of MAPK, PI3K–Akt and EGFR pathway, respectively." (PMID 29455673, 2018). "In summary, our findings revealed a seven-lncRNA signature that predicted OS of NSCLC patients, especially in those with early tumor stage and carrying wild-type KRAS or EGFR." (PMID 30205363, 2018). "It therefore was approved for first-line treatment of patients with mNSCLC whose tumors have high PD-L1 expression (tumor proportion score (TPS) ≥ 50%) and wild type of EGFR or ALK genes." (PMID 30159341, 2018). "In a xenograft model, LY3164530 had more anti-tumor effect in comparison to emibetuzumab and cetuximab, and was effective against NSCLC resistant to EGFR inhibitors." (PMID 30134579, 2018). "Cetuximab, an epidermal growth factor receptor (EGFR) inhibitor, binds to antigen on the surface of tumor cells and exhibits its anti-tumor activity through ADCC." (PMID 29973504, 2018). "The dual tyrosine kinase inhibitor AEE788 is utilized to inhibit EGFR and VEGFR binding on endothelial cells and resulted in apoptosis in both tumour and endothelial cells." (PMID 29455663, 2018). "IP experiments performed with anti-EGFR or E-cadherin Abs on OAW42 cell lysates demonstrated that EGFR and E-cadherin form a biochemical complex in these tumor cells." (PMID 29996940, 2018). "Using a cohort of patients whose tumors underwent comprehensive genomic and targeted immune transcriptomic analysis, we characterized the immune gene expression profile of EGFR mutant and Nrf2 altered NSCLC tumor samples." (PMID 30400822, 2018). "The protein levels of EGFR, ITGB4 and p-FAK were increased in tumor tissues, as compared with in normal tissues." (PMID 30479571, 2018). "In the case of tumor size, the biggest and smallest tumors were observed among patients with EGFR underexpression or MSI1 overexpression and patients with EGFR/MSI1 overexpression, respectively (5.67 ± 3.18 and 3.5 ± 0.58 cm)." (PMID 30202417, 2018). "Interestingly, the combination of Dasatinib and Gefitinib (an EGFR inhibitor) presents anti-tumor properties that are superior to those of platinum-based combinations, indicating that this combination may be a promising new treatment modality to be tested in the clinic." (PMID 29423044, 2018). "We nonetheless compared our data to gene signatures from the other isogenic HNSCC resistant model 1CC8, an independent resistant model to an EGFR inhibitor in NSCLC, and human tumor data from HNSCC patients before cetuximab treatment." (PMID 29792227, 2018). "PGE2 has been reported to transactivate and internalize into the nucleus receptor tyrosine kinases such as Epidermal growth factor receptor (EGFR), thereby supporting tumor progression." (PMID 29599917, 2018). "Although the effect of erlotinib, another first-generation EGFR-TKI, on tumor growth in vivo in combination with the GLUT1 inhibitor is yet to be tested, our in vitro results suggest erlotinib would be effective similarly to gefitinib." (PMID 30220973, 2018). "Non-small cell lung cancer is an important tumor type for EGFR targeted therapy and many NSCLC express high level of EGFR." (PMID 30323890, 2018). "The majority of the biomarkers studied are involved in tumor cell proliferation, of which HER2, EGFR, cyclin D, KI67 and MTOR were the most frequently reported." (PMID 30185893, 2018). "Epidermal growth factor receptor (EGFR) is thought to play a role in the regulation of cell proliferation; with its activation stimulating tumour growth." (PMID 30054711, 2018).
tumor (continued). "Remarkably, in the tumor from mice treated with LZ-8 coupled with KIF, p-JNK and c-Met were much higher and EGFR was significantly higher than those of the LZ-8 alone group." (PMID 30577605, 2018). "Non-squamous NSCLC patients with EGFR mutation benefited from gefitinib and afatinib with increased tumor response rate and prolonged progression-free survival compared to cytotoxic chemotherapy, while sorafenib may derive clinical benefit to NSCLC patients with wild-type EGFR." (PMID 29515689, 2018). "In order to support this pharmacokinetic behavior of the bivalent tracer [64Cu]Cu-α-EGFR-EGFR–NODAGA TM, time-activity curves (TAC) of regions of interest (ROI) derived from dynamic PET studies of four analyzed A431-Luc tumor bearing mice were estimated." (PMID 29876011, 2018). "Overexpression of EGFR, which has been reported in up to 30% of solid tumors including 90% of OSCC, generally correlates with a poor prognosis and promotes tumor proliferation." (PMID 29321718, 2018). "On the molecular level, dramatic decreases of the key RTKs, EGFR, and c-Met, and one of the downstream signal molecule p-JNK were observed in tumors from mice treated with LZ-8 compared with those in the tumor from untreated (con) group." (PMID 30577605, 2018). "In EGFR-mutant NSCLC patients, ANKRD1 was overexpressed in the tumor after the failure of EGFR-TKI therapy, especially after long-duration EGFR-TKI treatments." (PMID 30291293, 2018). "Epidermal growth factor receptor is highly expressed in a variety of solid tumors, including NSCLC, and its activation has been shown to promote processes involved in tumor cell proliferation, angiogenesis, invasion, metastasis, and inhibition of apoptosis." (PMID 29633504, 2018). "Specifically, an extensive crosstalk between epidermal growth factor receptor (EGFR) and ER mediated pathways is well documented in several tumor types." (PMID 30373552, 2018). "Upon binding to the ligand, EGFR activates various downstream signaling molecules including Ras, PI3K, phospholipase C-γ (PLC-γ), and JAK leading to cell survival, cell growth, and tumor progression." (PMID 29455658, 2018). "Recent data has demonstrated that RTKs, such as MET, EGFR, and PDGFR, regulate microRNA-134 in GBM, while microRNA-134 acts as a tumor-suppressive hub and controls KRAS and STAT5B expression levels." (PMID 29455648, 2018). "Vδ2 T cells can also be elicited to develop anti-tumor activity through ADCC; this can be obtained using therapeutic antibodies, such as the anti-EGFR huAb Cet." (PMID 29867975, 2018). "EGFR was thus activated in DFSP infiltrative periphery and DFSP-T, and EGFR signaling in DFSP tumor progression preferentially involved TOR and STAT5a/b downstream effectors, but not ERK in the MAPK pathway." (PMID 29492209, 2018). "Our results provide a molecular mechanism by which ETV6 suppresses tumor progression through transcriptional regulation of TWIST1 and disruption of EGFR-RAS signaling." (PMID 29455655, 2018). "Concurrent inhibition of EGFR and IGF1R obstructed the initiation of resistance to gefitinib treatment and reverse the resistant phenotype both in A431 cell line and tumor xenografts." (PMID 29455669, 2018). "Inhibition of CTLA-4 induced the upregulation of PD-L1, as well as the activation of the EGFR pathway in NSCLC cells, highlighting a distinct function of CTLA-4 in tumor cells compared to T cells." (PMID 30577587, 2018). "From the CDX and PDX in vivo models, we found that only when there was a higher expression of EGFR did the combination of GNA and erlotinib enhance the anti-tumor effect of erlotinib." (PMID 29449529, 2018). "Compared with in normal tissues, the level of miR-133b was decreased, while EGFR and ITGB4 mRNA levels were enhanced in tumor tissues." (PMID 30479571, 2018). "Lapatinib inhibits MAPK and PI3K signal transduction in EGFR and HER2 overexpressing tumor cell lines." (PMID 29455664, 2018).
tumor (continued). "Results from this analysis are consistent with prior knowledge of EGFR-mutant NSCLC, demonstrating a PD-L1 low, GzmB low, IFNG low and TGFbeta high immune phenotype, suggesting a suppressive tumor microenvironment." (PMID 30400822, 2018). "For example, activated EGFR found in EVs is sufficient to induce EGFR and VEGFR signaling in recipient endothelial cells, and blocking EV-mediated EGFR transfer decreased tumor growth and angiogenesis." (PMID 30071693, 2018). "We found a correlation between BAG3 and EGFR expression in TNBC cell lines and determined that BAG3 can regulate tumour cell proliferation, migration and invasion in EGFR expressing TNBC cells lines." (PMID 29644001, 2018). "Collectively, these reports suggest that EGFR–ERK signalling is a key driver of stem/progenitor cell proliferation and tumour progression in the intestinal epithelium in both mice and humans." (PMID 29872037, 2018). "Another strategy is to create a pseudoreceptor system using single-chain antibody fragments to retarget the virus to tumor-specific CD38, epidermal growth factor receptor (EGFR), or EGFR mutant vIII (EGFRvIII)." (PMID 29949934, 2018). "However, withdrawal of an EGFR TKI at the onset of resistance may lead to rapid tumour growth." (PMID 29382302, 2018). "We further examined the effect of P.A treatment on EGFR, AMPK, mTOR, Akt, and death receptor cascades in protein extracts derived from tumor tissues." (PMID 29899551, 2018). "In a second in vivo model, the tumor cells expressed low levels of FR-α, and high levels of EGFR, the combination of the Onc.Ad with CAR-T cells resulted in sustained reduction of tumor volume compared to single agent treatments." (PMID 30298067, 2018). "Modes of clinical failure for EGFR-TKI therapy are typically based on the duration of disease control and evaluation of the tumor burden and clinical symptoms." (PMID 29789021, 2018). "Dual repression of EGFR and HER-2 has been shown to impair PCa tumour cell proliferation and survival." (PMID 30134822, 2018). "Despite of multimodal up-to-date treatment regimens consisting of local intervention including surgery of metastases, chemotherapy in combination with monoclonal EGFR and VEGF antibodies, many patients still experience tumor recurrence and have a poor outcome." (PMID 30181810, 2018). "As a tumor suppressor, ZEB1 suppressed growth by increasing microRNA-200 targets to antagonize ERBB3, a driver of mutant EGFR-dependent cell growth." (PMID 32309604, 2018). "There was a significant correlation between EGFR/MSI1 mRNA expression and grade of tumor differentiation in which 5/7 (71.43%) tumors with concomitant overexpression of these markers were moderately differentiated (p = 0.02)." (PMID 30202417, 2018). "And both our in vitro and in vivo experiments delicately avoid the complexity because we chose an applicable short time point to conduct Lycorine treatment to exclude EGFR downregulation effects on in vitro GBM cells proliferation and in vivo GBM tumor growth." (PMID 30016965, 2018). "The most foremost effect of elevated cholesterol is higher raft formation and momentous enrichment of specific proteins and receptors such as EGFR, IGF-1, CD44, and CD24 involved in cellular signaling mediating tumor progression and invasion." (PMID 30186863, 2018). "To demonstrate that tumor gene reprogramming promoted by EGF and PGE2-induced nuclear EGFR is critical for tumor progression, we have assessed cell proliferation by BrdU incorporation assay in NSCLC cells." (PMID 29599917, 2018). "The stimulation with both growth factors ensures that both signaling pathways initiated from EGFR and MET are activated, which mimics physiological conditions in the tumor micro milieu." (PMID 30227653, 2018). "These tumors contain certain features of human GBM such as the presence of pleomorphic cells, tumor invasion into the surrounding brain, expression of genes involved in human GBM, such as PDGFb, EGFR, IGF-1, and Erb3." (PMID 30271342, 2018).
tumor (continued). "The inhibitory effects of KYA1797K on the tumor organoids correlated with the reduction in the β-catenin, pan-RAS, EGFR, and PCNA levels." (PMID 30459318, 2018). "After intratumoral administration, the tumor-specific viral transgene expression was enhanced through virus retargeting in both HER2+ and EGFR+ xenograft models by 20- to 34-fold." (PMID 29386504, 2018). "In the present study we investigated the potential of four miRNAs targeting EGFR to predict response to second and third-line therapy with erlotinib in patients with NSCLC based on their expression level in tumor specimens at diagnosis." (PMID 29689091, 2018). "Along with the mentioned proteins, we also found with Western blot analysis the AI tumorspheres to significantly up-regulate other highly tumorigenic proteins involved in aggressive tumor behavior, including PDGFRβ, VEGFR2 and EGFR compared to the AD cells." (PMID 29298329, 2018). "Activation of the NTSR1 receptor leads to activation of the EGFR family: in particular EGFR, ErbB2/HER2, and ErbB3/HER3, which in turn are responsible for signal transduction within the tumor cell." (PMID 29467963, 2018). "Here, we explored continuous and pulsatile dosing strategies in an EGFR-mutant GBM cell line, and used mathematical and statistical modeling to determine optimal lapatinib dosing schedules for inhibiting tumor growth." (PMID 29293494, 2018). "Tumor and blood samples from 69 stage IIIB-IV NSCLC patients acquired resistance to EGFR-TKI were collected." (PMID 30103780, 2018). "Thus, in ordinary clinical practice based on the guidelines for the prevention and treatment of anti‐EGFR ab‐related dermatologic toxicities, the alleviation of grade 3 skin toxicity reactions by prophylactic management might result in no impairment of either HRQOL or skin‐related QOL." (PMID 30051609, 2018). "Initially, first-generation TKIs such as gefitinib (for EGFR-positive NSCLC) and crizotinib (for EML4–ALK fusion-positive NSCLC) demonstrate strong anti-tumor activity; however, most patients develop resistance and subsequently relapse." (PMID 29764505, 2018). "The anti-stem cell and anti-tumor activity of ICG-001 in combination with erlotinib in these EGFR mutant NSCLC models is well tolerated and a very effective EGFR TKI combination in our studies." (PMID 30097569, 2018). "Original tumor, R2J, cultured in monolayer (2D) and in spheres showed a persistence expression of CD44, CD56 (except in monolayer), EGFR, Ki67, Nestin, and vimentin." (PMID 30583471, 2018). "We assessed cell proliferation in vitro and tumor growth/stroma formation in derived xenograft models in response to a MET TKI (SGX523) and correlated with EGFR-MET dimerization assessed by Förster Resonance Energy Transfer (FRET)." (PMID 28141869, 2017). "IHC staining showed that labeled BM-PDXs retained expression of EGFR, CK5, and HER2, suggesting that dissociated/labeled cells are capable of reconstituting tumor heterogeneity of BM-PDXs." (PMID 29164052, 2017). "In almost all samples derived from different EGFR inhibitor resistant tumors, protein levels of phospho-MAPK were low, with the exception of the one tumor resistant to gefitinib-afatinib-osimertinib, in which we detected the KRAS-G12D mutation." (PMID 28416737, 2017). "In this study, using a Drosophila tumour model the authors demonstrate that depletion of Arf6, a Ras-related GTP-binding protein activated by EGFR, supresses oncogenic Ras driven overgrowth via modulation of Hedgehog signalling." (PMID 28281543, 2017). "Phosphoproteomic analyses of 41 NSCLC cell lines and 150 NSCLC tumours revealed that AXL phosphorylates tyrosine residues, similar to other oncogenic kinases such as EGFR, c-Met, and ALK31." (PMID 29259259, 2017).
tumor (continued). "WES of this second tumor recurrence again showed chromosome 10 and CDKN2A deletion but even more interestingly still high ploidy of the EGFR/MDM4 loci (>10 and >6, respectively)." (PMID 28153049, 2017). "Blocking experiment with excess dose of cetuximab resulted in 56.7% reduced tumor uptake of 64Cu-PCTA-cetuximab, indicating the EGFR targeting specificity of 64Cu-PCTA-cetuximab." (PMID 29190900, 2017). "And EGFR is important for tumor cell motility and invasion, and HER2 for tumor cell intravasation in vivo experiments." (PMID 28427196, 2017). "HER2YVMA was further shown to increase phosphorylation of HER2, EGFR, and downstream signal transducers including AKT and ERK, transform bronchial and mammary epithelial cells, and promote tumor formation in nude mice." (PMID 29371993, 2017). "Other upstream genes of ERK signaling pathway such as EGFR, FGFR3 were also enriched in resistant tumor cells." (PMID 29296238, 2017). "Proper tumor classification is likely to be critical for arriving at thorough conclusions regarding new HER2 and EGFR based treatment regimes." (PMID 28388586, 2017). "To further investigate the mechanisms of antitumor efficacy of fusion proteins in vivo, we analyzed the phosphorylation and total expression levels of EGFR, IGF-1R, AKT and ERK in xenograft tumor tissues by Western blot." (PMID 28460483, 2017). "Because EGFR-TKI treatment abrogated the growth promotion induced by PMPA in vitro, we next treated PC-10 tumour xenografts with erlotinib in vivo." (PMID 28642617, 2017). "The inhibition of HSP90 by 17-AAG depletes ErbB2, EGFR, phosphorylated AKT, and other oncogenic proteins involved in tumor progression." (PMID 29097911, 2017). "As a consequence of c-MET/EGFR inhibition, stable SKOV3 cells that expressed miR-206 displayed a retarded cell proliferation and tumor growth." (PMID 29291022, 2017). "As the major upstream regulator of HIF-1α expression, EGFR/PI3K/AKT/mTOR and MAPK/ERK1/2 pathways were simultaneously suppressed by F2 in U87 cells and xenograft tumor model." (PMID 29156717, 2017). "Since the epidermal growth factor receptor (EGFR) is overexpressed in a high range of CRC tumors, it represents an auspicious target for tumor-specific NIS gene delivery via actively targeted nanoparticle transfer." (PMID 29190908, 2017). "Epidermal growth factor receptor (EGFR) and hepatocyte growth factor receptor (c-Met) are two receptor tyrosine kinases known to contribute to tumor progression." (PMID 28978320, 2017). "CD44 receptors are connected to the signalling cascade of EGFR and the PI3K/Akt and thus can significantly affect tumor progression." (PMID 29029509, 2017). "Dual targeting of EGFR and ErbB3 most effectively blocked p-Erk and p-Akt in the presence of EGFR ligands and HRG, which translated into synergistic inhibition of tumor growth in A549 and H322." (PMID 28725482, 2017). "Preclinical data was used to develop a mechanism-based computational model linking cell surface receptor (EGFR) activation, the MAPK signaling pathway, and tumor growth." (PMID 28649441, 2017). "Within the nucleus, EGFR induces the expression of iNOS, COX-2, c-Myc and cyclin D1, thus reprogramming important tumor growth parameters, including tumor cell proliferation and malignant progression." (PMID 28415726, 2017). "We identified minimal cellular differences between the three in vivo xenograft models (proliferation rate, alternate (non-EGFR) RTK expression, and MAPK-dependence) that suffice to capture the differential tumor growth response patterns between them." (PMID 28649441, 2017). "Thus, some hypothesize that NSCLC patients with EGFR mutation and brain metastases could receive EGFR-TKI alone first, and brain RT may be delayed until tumor progression on brain imaging or symptomatic progression, thereby delaying radiation-related neurotoxicitis." (PMID 29340055, 2017). "FISH analysis also suggested that concurrent genetic alteration of EGFR and MET occurred in individual tumor cells." (PMID 28287179, 2017).